RAP1A (RAP1A, member of RAS oncogene family)
Description:
Counteracts the mitogenic function of Ras, at least partly because it can interact with Ras GAPs and RAF in a competitive manner. Together with ITGB1BP1, regulates KRIT1 localization to microtubules and membranes. Plays a role in nerve growth factor (NGF)-induced neurite outgrowth. Plays a role in the regulation of embryonic blood vessel formation. Involved in the establishment of basal endothelial barrier function. Facilitates the progressive accumulation of CDH1 at mature desmosome junctions via cAMP-dependent signaling and its interaction with PKP3. May be involved in the regulation of the vascular endothelial growth factor receptor KDR expression at endothelial cell-cell junctions.
Synonyms: KREV1; KREV-1; SMGP21; C21KG; G-22K; RAP1
Tractability: Small molecule: a structure with a bound ligand is known. Antibody: UniProt places it where antibodies can reach, with high confidence; its Gene Ontology location is reachable by antibodies, with high confidence. PROTAC: ubiquitination databases record sites on it; its protein half-life has been measured; a small molecule that binds it is known.
Target class: Enzyme; Hydrolase
Gene: Protein-coding gene on chromosome 1 (111,542,218 to 111,716,691, forward strand). Ensembl gene ENSG00000116473.
Subcellular location: Cell membrane; Cytoplasm; Cytoplasm, perinuclear region; Cell junction; Early endosome
Pathways (Reactome):
Signal Transduction: ARMS-mediated activation; Frs2-mediated activation; GRB2:SOS provides linkage to MAPK signaling for Integrins; Integrin signaling; MAP2K and MAPK activation; MET activates RAP1 and RAC1; p130Cas linkage to MAPK signaling for integrins
Disease: Paradoxical activation of RAF signaling by kinase inactive BRAF; Signaling by BRAF and RAF1 fusions; Signaling by RAF1 mutants; Signaling by high-kinase activity BRAF mutants; Signaling by moderate kinase activity BRAF mutants; Signaling downstream of RAS mutants
Immune System: Neutrophil degranulation; Rap1 signalling
Metabolism: Glucagon-like Peptide-1 (GLP1) regulates insulin secretion
Gene Ontology:
Molecular function: protein binding; protein-containing complex binding; GTPase activity; guanyl-nucleotide exchange factor activity; G protein activity; GTP binding; small GTPase binding
Biological process: cellular response to cAMP; establishment of endothelial barrier; protein localization to plasma membrane; Rap protein signal transduction; regulation of cell junction assembly; regulation of neurotransmitter receptor localization to postsynaptic specialization membrane; cellular response to nerve growth factor stimulus; negative regulation of synaptic vesicle exocytosis; nerve growth factor signaling pathway; positive regulation of ERK1 and ERK2 cascade; positive regulation of GTPase activity; positive regulation of neuron projection development; positive regulation of protein kinase activity; positive regulation of vasculogenesis; adenylate cyclase-activating G protein-coupled receptor signaling pathway; cellular response to forskolin; liver regeneration; negative regulation of collagen biosynthetic process; positive regulation of D-glucose import; positive regulation of Fc receptor mediated stimulatory signaling pathway; positive regulation of phagocytosis; response to antineoplastic agent; response to carbohydrate; signal transduction
Cellular component: cytoplasm; extracellular exosome; glutamatergic synapse; perinuclear region of cytoplasm; cell junction; cytosol; early endosome; endosome membrane; late endosome; plasma membrane; specific granule membrane; sperm midpiece; anchoring junction; dense core granule; guanyl-nucleotide exchange factor complex; membrane; neuron projection; phagocytic vesicle
Genetic constraint (gnomAD): Loss-of-function variants: 4 observed, 21.14 expected, observed/expected ratio (o/e) 0.19, 90% interval 0.092 to 0.43. The upper end of that interval is the gene's LOEUF score, 0.43, which puts it in group 1 of 6, group 1 being the genes least tolerant of losing a copy. Missense variants: 99 observed, 174.96 expected, observed/expected ratio (o/e) 0.57, 90% interval 0.48 to 0.67. Synonymous variants: 58 observed, 67.62 expected, observed/expected ratio (o/e) 0.86, 90% interval 0.69 to 1.07.
Homologues: Orthologues: chimpanzee RAP1A (100% identical), dog RAP1A (100% identical), guinea pig RAP1A (100% identical), macaque RAP1A (100% identical), mouse Rap1a (100% identical), pig RAP1A (100% identical), rabbit RAP1A (100% identical), rat Rap1a (100% identical). Paralogues in human: RAP1B (95% identical), RAP2A (61% identical), RAP2B (61% identical), RAP2C (60% identical), KRAS (54% identical), HRAS (53% identical), RRAS2 (53% identical), MRAS (52% identical), RRAS (52% identical), NRAS (51% identical), RALA (49% identical), RALB (49% identical), and 23 more.
Diseases named in the same sentence as RAP1A in open-access papers:
RAP1A is named in the same sentence as 82 diseases in open-access papers, as found by Europe PMC text mining. Sharing a sentence is not in itself a finding about the gene and the disease. The quoted sentences say what the papers report.
breast cancer (13 papers, 2013 to 2023). A primary or metastatic malignant neoplasm involving the breast. "On the other hand, Rap1A expression remains almost unchanged in prostate and breast cancer while it decreases in uterine cancer (in both “metastatic” and “not metastatic” groups)." (PMID 35565390, 2022). "Model 2 included four candidate predictors specific for breast cancer in this study: Ras-related protein Rap-1A (RAP1A, LVVLGSGGVGK), Integrin alpha-IIb (ITGA2B, VYLFLQPR), FLNA (ANLPQSFQVDTSK), and Talin-1 (TLN1, LAQAAQSSVATITR)." (PMID 33267867, 2020). "Data from our lab shows that miR-149 suppresses Rap1a/b in basal breast cancer cells and impairs cell spreading, migration, and invasion in vitro, and lung metastasis formation in vivo." (PMID 25630670, 2015). "In order to determine if Rap1A signaling is involved in LPA-mediated breast cancer cell invasion, we depleted Rap1A from the highly aggressive breast cancer MDA-MB-231 cells by stably expressing two individual Rap1A shRNA constructs (shRNA-1 and shRNA-2)." (PMID 23405264, 2013). "Depletion of Rap1A expression significantly impaired LPA-stimulated migration of breast cancer cells and invasiveness in three-dimensional Matrigel cultures." (PMID 23405264, 2013). "Rap1A protein expression is also higher in aggressive breast cancer cells (MDA-MB-231 and Hs578t) relative to the weakly invasive MCF-7 cells or non-malignant MCF10A mammary cells." (PMID 23405264, 2013). "Breast cancer cells stably expressing Rap1A shRNA showed a pronounced reduction of LPA-stimulated lamellipodia formation in cells at the leading edge compared to cells expressing scrambled shRNA." (PMID 23405264, 2013). "In order to quantify Rap1A expression in vivo, Rap1A mRNA levels were measured in an array of 48 cDNA samples derived from breast cancer patients at Stages 0-IV of the disease." (PMID 23405264, 2013). "The effects of Rap1A knockdown on breast cancer cell invasion was also examined using rigid three-dimensional (3D) cell invasion assays using a reconstituted extracellular matrix (Matrigel) that mimics the in vivo micro-environment." (PMID 23405264, 2013). "We also observed increased levels of Rap1A protein in invasive breast cancer cells (MDA-MB-231 and Hs578T) compared to non-invasive MCF-7 cells or the non-malignant MCF-10A cells." (PMID 23405264, 2013). "Reduction of Rap1A expression using shRNA sequences inhibited LPA-stimulated breast cancer cell migration and formation of invasive stellate structures in 3D cultures." (PMID 23405264, 2013). "Rap1a–RADIL signaling performs a critical role in the progression of breast cancer." (PMID 31448237, 2019). "Moreover, RAP1A-RADIL inside-out signaling which is essential for breast cancer cell migration and invasion, can be inhibited by KLF14 through binding to C-terminal PDZ domain of RADIL and restricting RADIL from interacting with activated RAP1A spatially." (PMID 31448237, 2019). "Interestingly, also downregulated in ADCs was miR-149, which was demonstrated previously to have tumor suppressor capacity in breast cancer migration and invasion by targeting small GTPases Rap1a and Rap1b." (PMID 28787442, 2017). "We identified a novel interaction between LPA1 and Rap1A in breast cancer cells." (PMID 23405264, 2013). "Although it has been demonstrated that IQGAP1 directly interacts with Rap1A in vitro, using purified proteins, whether or not this association occurs in breast cancer cells is not known." (PMID 23405264, 2013). "Many of these genes have known roles in cancer gene networks such as the proto-oncogenes JUN and FOS, RAP1A (RAS-related protein 1A), ITGB5, as well as BRCA2 (Breast cancer 2, early onset) and PCNA (Proliferating cell nuclear antigen)." (PMID 26448646, 2015).
breast cancer (continued). "Nevertheless, the combined treatment of B02 cells with ZOL+US did induce intracellular accumulation of unprenylated Rap1A in these tumor cells, further demonstrating that US maximized the antitumor effect of ZOL in B02 breast cancer cells in vitro." (PMID 26578234, 2015). "Rap1A has been shown to interact directly with the actin-binding protein, IQGAP1, which has established roles in breast cancer cell migration and invasion." (PMID 23405264, 2013). "We recently demonstrated in breast cancer cells lines, direct interaction of KIF14 with Radil, a crucial mediator of Rap1a-mediated integrin inside-out signaling, thereby controlling Radil-Rap1a activity at the cell membrane and promoting cell adhesion and migration." (PMID 24626475, 2014). "Thus our data establish novel roles for Rap1A and IQGAP1 as critical regulators of LPA-induced breast cancer cell migration and invasion." (PMID 23405264, 2013). "We next determined whether or not Rap1A proteins were altered in three well-established human breast cancer cell lines (MCF-7, MDA-MB-231, and Hs578T) compared to non-malignant mammary epithelial (MCF-10A) cells." (PMID 23405264, 2013).
esophageal squamous cell carcinoma (5 papers, 2013 to 2025). Esophageal squamous cell carcinoma (ESCC) is a type of esophageal carcinoma (EC) that can affect any part of the esophagus, but is usually located in the upper or middle third. "RAP1A, also over-expressed, is linked to esophageal squamous cell carcinoma, enhancing metastasis through increased cell migration and invasion." (PMID 39941055, 2025). "For example, hsa-mir-196a which ranks the second in the top 50 has been confirmed that its binding-site SNP (rs6573) can regulate RAP1A expression, which contributes to the risk and metastasis of esophageal squamous cell carcinoma." (PMID 29515453, 2018). "For instance, the variant A allele of RAP1A rs6573 enhanced the binding ability of miR-196a, leading to an increased miRNA-mediated RAP1A repression, and this SNP functioned as a potential personal diagnostic marker for esophageal squamous cell carcinoma." (PMID 24146953, 2013). "Through AKT signaling, RAP1A promotes metastasis in esophageal squamous cell carcinoma (ESCC), and an aggressive phenotype in colorectal cancer through PTEN/FOXO3/CCND1 pathway." (PMID 33958005, 2021). "Furthermore, it was shown that in esophageal squamous cell carcinoma, a risk SNP in the 3′UTR of the RAP1A gene, affects the binding site of miRNA-196a." (PMID 23752272, 2013).
ovarian carcinoma (5 papers, 2015 to 2023). A malignant neoplasm originating from the surface ovarian epithelium. "Herein, we investigated the role of Rap1A in some ovarian cancer cell lines and tried to uncover the Rap1A associated mechanism in ovarian cancer." (PMID 27925454, 2016). "It was reported that Rap1A promoted ovarian cancer tumorigenesis and metastasis via activating ERK, MAPK, Notch pathways." (PMID 32226523, 2020). "Here, we show that Rap1A promotes ovarian cancer tumorigenesis and metastasis via stimulating cell proliferation, migration and invasion both in vivo and in vitro." (PMID 27925454, 2016). "In summary, our study provided clear data to show that Rap1A promotes ovarian cancer cell proliferation, migration and invasion via the ERK/p38 and Notch signal pathways." (PMID 27925454, 2016). "In this study, by silencing or overexpression of Rap1A and drug treatment, we investigated the effects of Rap1A on ovarian cancer cell proliferation, invasion, and metastasis." (PMID 27925454, 2016). "To investigate the function of Rap1A in human ovarian cancer, we first detected the expression level of Rap1A in various human ovarian cancer cell lines." (PMID 27925454, 2016). "In this study, we first investigated the function of Rap1A in ovarian cancer cell proliferation, migration and invasion through up‐regulation or down‐regulation of Rap1A." (PMID 27925454, 2016). "We found that Rap1A functions as an oncogene to promote ovarian cancer metastasis through activation of the ERK/p38 and Notch signaling." (PMID 27925454, 2016). "Together, these observations demonstrated that Rap1A exerts a strong effect on the tumor‐initiation and metastatic ability of ovarian cancer cells." (PMID 27925454, 2016). "To determine whether Rap1A contributes to ovarian cancer tumorigenesis and metastasis in vivo, we performed animal assays with cancer cells expressing Rap1A shRNA or Rap1A cDNA." (PMID 27925454, 2016). "Besides the in vitro findings, our data also illustrated that Rap1A facilitates the tumorigenic and metastatic behaviors of ovarian cancer cells in vivo." (PMID 27925454, 2016). "The function of Rap1B and Rap1A in ovarian cancer migration/invasion was then tested." (PMID 25569036, 2015). "Thus, Rap1A may promote ovarian cancer metastasis at least partially through the up‐regulation of MMP9." (PMID 27925454, 2016). "Further analysis showed that ovarian cancer patients with high level of CITED2, LYVE1, OGN, RAP1A, and TBC1D22A had a poor prognosis that that with level of CITED2, LYVE1, OGN, RAP1A, and TBC1D22A (all p < 0.05)." (PMID 37784081, 2023). "The protein level of CITED2, LYVE1, OGN, RAP1A, and TBC1D22A were higher in ovarian cancer tissues than that in normal tissues." (PMID 37784081, 2023). "This study is in agreement with a previous study correlating upregulation of Rap1A with enhanced EMT markers expression and ERK activation in ovarian cancer cells." (PMID 32906721, 2020). "Thus, Rap1A may positively regulate the Notch signaling to promote ovarian cancer cell initiation." (PMID 27925454, 2016). "Therefore, Rap1A may function to promote ovarian cancer cell migration and invasion." (PMID 27925454, 2016). "We found that the expression of MMP9 but not MMP2 was markedly altered in both Rap1A overexpression and silencing ovarian cancer cells." (PMID 27925454, 2016). "However, the precise function of Rap1A in ovarian cancer is still not understood." (PMID 27925454, 2016). "Furthermore, with respect to the distinct isoforms, Rap1A and Rap1B, our data revealed that only depletion of Rap1B, but not Rap1A, significantly inhibited migration/invasion of ovarian cancer cells, suggesting the dominant role of Rap1B in promoting migration/invasion." (PMID 25569036, 2015).
lung cancer (4 papers, 2012 to 2023). A malignant neoplasm involving the lung. "In another study, miR‐501‐3p directly targeted the RAS oncogene RAP1A to repress cell proliferation in non‐small cell lung cancer." (PMID 34595849, 2021). "In accordance with our results, researchers found RAP1A also promotes the malignant proliferation of other tumors such as brain, prostate and lung cancer." (PMID 30064475, 2018). "In addition, miR‐501‐3p promotes osteosarcoma cell proliferation by targeting BCL7A23 and the miRNA can directly target the RAS oncogene RAP1A to repress non‐small cell lung cancer cell proliferation." (PMID 34595849, 2021). "In addition, we are the first to define the regulation of STAT3 and RAP1A by a single miRNA in the context of lung cancer, and provide the first preliminary evidence showing that STAT3 expression is an intrinsic determinant of paclitaxel response in lung cancer cells." (PMID 22723956, 2012).
cervical cancer (3 papers, 2020 to 2023). A primary or metastatic malignant neoplasm involving the cervix. "Additionally, miR-337-3p suppresses proliferation, migration, and invasion of cervical cancer cells by targeting Rap1A and the expression levels of miR-337-3p is related to better clinicopathological characteristics of cervical cancer." (PMID 32934214, 2020).
endothelial dysfunction (3 papers, 2021 to 2025). In vascular diseases, endothelial dysfunction is a systemic pathological state of the endothelium (the inner lining of blood vessels) and can be broadly defined as an imbalance between vasodilating and vasoconstricting substances produced by (or acting on) the endothelium. "Dysregulation of Rap1a has been associated with endothelial dysfunction, a hallmark of hypertension." (PMID 41294886, 2025). "The compound effect of endothelial loss of both Rap1A and Rap1B isoforms is severe endothelial dysfunction and hypertension." (PMID 34222255, 2021). "Additionally, dysregulation of Rap1a has been linked to endothelial dysfunction, a hallmark of hypertension." (PMID 41294886, 2025). "Here, we demonstrate that endothelial dysfunction resulting from knockout of both Rap1A and Rap1B isoforms is ameliorated by exogenous L-Arg administration to rescue NO-dependent vasorelaxation and blood pressure." (PMID 34222255, 2021). "These mechanistic insights, combined with mouse models and human transcriptomic analyses, highlight the differential physiological roles of Rap1A and Rap1B and their implications for vascular pathologies, including inflammation, tumor angiogenesis, and endothelial dysfunction." (PMID 40508181, 2025).
glioblastoma (3 papers, 2016 to 2021). The most malignant astrocytic tumor (WHO grade IV). "In glioblastoma, researchers demonstrated that Rap1A promotes glioblastoma proliferation and tumor growth." (PMID 27925454, 2016). "Rap1a and Rap1b are 95% homologous, but differences in subcellular localization of two isoforms and their mechanisms of activation resulted in their distinctive functions and roles in glioblastoma cell proliferation." (PMID 31921670, 2019).
glioma (3 papers, 2020 to 2023). A benign or malignant brain and spinal cord tumor that arises from glial cells (astrocytes, oligodendrocytes, ependymal cells). "In additional, the authors indicated that miR-410 exerts tumor-suppressing functions (inhibitory effects on tumor cell proliferation, migration, and invasion) in glioma by directly targeting mRNA 3′-untranslated regions (3′UTR) Ras-related protein 1A (RAP1A)." (PMID 35646622, 2022). "Increased Rap1a expression also correlated with GBM compared to other glioma tumors, as well as increasing tumor grade." (PMID 32102991, 2020).
Hypertension (3 papers, 2015 to 2025). The presence of chronic increased pressure in the systemic arterial system. "This study advances our understanding of the molecular pathways underlying hypertension and cardiac remodeling, focusing on the roles of RAGE and Rap1a in AngII-mediated effects." (PMID 41294886, 2025). "Future studies should elucidate the molecular interplay between Rap1a and Epac in hypertension and evaluate pharmacological interventions." (PMID 41294886, 2025). "Instead, the most profound defect in total Rap1 (Rap1A + Rap1B), EC-specific KO (Rap1iΔEC) mice is endothelial dysfunction due to a decreased NO bioavailability defect, evidenced by impaired vasorelaxation defect ex vivo and hypertension in vivo." (PMID 34222255, 2021). "Hypertension drives cardiovascular disease through maladaptive remodeling, with RAGE, Rap1a, and AngII interacting within a complex signaling network that promotes hypertrophy, inflammation, and fibrosis." (PMID 41294886, 2025).